CIRBP (cold inducible RNA binding protein)
Description:
Cold-inducible mRNA binding protein that plays a protective role in the genotoxic stress response by stabilizing transcripts of genes involved in cell survival. Acts as a translational activator. Seems to play an essential role in cold-induced suppression of cell proliferation. Binds specifically to the 3'-untranslated regions (3'-UTRs) of stress-responsive transcripts RPA2 and TXN. Acts as a translational repressor (By similarity). Promotes assembly of stress granules (SGs), when overexpressed.
Synonyms: CIRP
Tractability: Small molecule: a structure with a bound ligand is known. PROTAC: ubiquitination databases record sites on it; its protein half-life has been measured.
Gene: Protein-coding gene on chromosome 19 (1,259,384 to 1,274,880, forward strand). Ensembl gene ENSG00000099622.
Subcellular location: Nucleus, nucleoplasm; Cytoplasm
Subcellular location (Human Protein Atlas): Nucleoplasm
Gene Ontology:
Molecular function: mRNA 3'-UTR binding; protein binding; RNA binding; small ribosomal subunit rRNA binding; translation repressor activity; nucleic acid binding
Biological process: mRNA stabilization; positive regulation of translation; response to UV; mRNA splicing, via spliceosome; response to cold; stress granule assembly; negative regulation of translation
Cellular component: cytoplasm; nucleoplasm; nucleus; cytoplasmic stress granule; spliceosomal complex
Genetic constraint (gnomAD): Loss-of-function variants: 9 observed, 21.9 expected, observed/expected ratio (o/e) 0.41, 90% interval 0.25 to 0.72. The synonymous counts are far from expectation, so gnomAD's model fits this gene poorly and the ratio says little. Missense variants: 453 observed, 411.6 expected, observed/expected ratio (o/e) 1.1, 90% interval 1.02 to 1.19. Synonymous variants: 215 observed, 163.66 expected, observed/expected ratio (o/e) 1.31, 90% interval 1.17 to 1.47.
Homologues: Orthologues: chimpanzee CIRBP (69% identical), pig CIRBP (58% identical), dog CIRBP (56% identical), mouse Cirbp (55% identical), guinea pig CIRBP (52% identical), tropical clawed frog cirbp (45% identical). Paralogues in human: RBMX (38% identical), RBMXL1 (37% identical), RBM3 (36% identical), RBMXL2 (31% identical), RBMY1B (28% identical), RBMY1F (28% identical), RBMY1J (28% identical), RBMY1A1 (28% identical), RBMY1D (28% identical), RBMY1E (27% identical), RBMXL3 (27% identical), HNRNPA3 (23% identical), and 24 more.
Diseases named in the same sentence as CIRBP in open-access papers:
CIRBP is named in the same sentence as 126 diseases in open-access papers, as found by Europe PMC text mining. Sharing a sentence is not in itself a finding about the gene and the disease. The quoted sentences say what the papers report.
Sepsis (60 papers, 2014 to 2026). Sepsis is defined as life-threatening organ dysfunction caused by a dysregulated host response to infection. "Cold-inducible RNA-binding protein (CIRP) is a damage-associated molecular pattern that is up-regulated during sepsis." (PMID 39907066, 2025). "Cold-inducible RNA-binding protein (CIRP), released into the circulation during sepsis, causes lung injury via an as yet unknown mechanism." (PMID 28128330, 2017). "A recent experimental study reports that during sepsis, the lactylation of cold-inducible RNA-binding protein (CIRP) facilitates its release from macrophages." (PMID 41531823, 2026). "Collectively, CIRBP serves as a central modulator of inflammasome-driven pathways in sepsis, linking tissue injury, RNA metabolism, and innate immunity." (PMID 40959087, 2025). "This population appears to be expanded during sepsis and is stimulated by cold-inducible RNA-binding protein (CIRP), which promotes NETosis through iNOS upregulation, as shown in CIRP-treated bone marrow-derived neutrophils." (PMID 40806591, 2025). "The cold-inducible RNA-binding protein (CIRBP) acts as a critical mediator of systemic inflammation in sepsis by integrating with inflammasome pathways." (PMID 40959087, 2025). "CIRBP antiserum as well as blockage of its receptors have been shown to reduce systemic inflammation, organ dysfunction, and mortality in in vivo sepsis and hemorrhagic shock model." (PMID 38361581, 2024). "Cold-inducible RNA-binding protein (CIRP) induces neutrophil reverse transendothelial migration (rTEM) in sepsis by increasing neutrophil elastase (NE) and decreasing JAM-C." (PMID 35356274, 2022). "CIRBP is involved in the development of brain ischemia, and extracellular CIRBP triggers inflammation and tissue injury in sepsis by inducing the formation of neutrophil extracellular traps in patients lungs." (PMID 34738012, 2021). "Cold-inducible RNA binding-protein (CIRP) is an 18-kDa nuclear RNA chaperone protein that is released extracellularly both passively after necrotic cell death and in response to sepsis, hemorrhage or ischemia–reperfusion injury." (PMID 33276725, 2020). "Cold‐inducible RNA‐binding protein (CIRP) is a small 172‐amino‐acid RNA chaperone protein 6 and is secreted into the extracellular space in inflammatory diseases such as sepsis, I/R injuries, and hemorrhagic shock (reviewed in 7)." (PMID 31724825, 2020). "Extracellular cold-inducible RNA-binding protein (CIRP) exaggerates inflammation and tissue injury in sepsis." (PMID 31000768, 2019). "Cold-inducible RNA-binding protein (CIRP) is a novel sepsis inflammatory mediator and C23 is a putative CIRP competitive inhibitor." (PMID 29434211, 2018). "Cold-inducible RNA-binding protein (CIRP) is a damage-associated molecular pattern (DAMP) molecule which stimulates proinflammatory cytokine release in hemorrhage and sepsis." (PMID 27217302, 2016). "Interestingly, lactylation of cold-inducible RNA-binding protein (CIRP) in macrophages induces the release of CIRP during sepsis." (PMID 40860191, 2025). "Hsp70 and HMGB1 are classical DAMPs and have been extensively investigated, whereas the inflammation-inducing DAMP property of extracellular CIRBP is a recent observation that has been shown to perpetuate the inflammatory response in hemorrhagic shock and sepsis patients." (PMID 31293389, 2019). "Cold-inducible RNA-binding protein (CIRP) is a widely distributed cold-shock protein that plays a proinflammatory role in sepsis and that may induce organ damage." (PMID 26361390, 2015). "Luteolin has also shown the ability to inhibit LPS-induced cold-inducible RNA-binding protein (CIRP) in macrophages, thus playing a critical role in suppressing sepsis-induced lung injury in neonatal mice." (PMID 39126050, 2024).
Sepsis (continued). "We further observed a significant correlation between the levels of cold-inducible RNA-binding protein (CIRP) in plasma and bronchoalveolar lavage fluid (BALF), as well as lactate levels, and the severity of post-sepsis ALI." (PMID 39465383, 2024). "Cold shock protein such as cold-inducible RNA-binding protein (CIRP) is a new DAMP molecule participating in acute live injury/failure and sepsis." (PMID 37426664, 2023). "Cold-inducible RNA-binding protein (CIRP), is a newly identified DAMP that aggravates inflammation and tissue injury, and induces respiratory failure in sepsis." (PMID 35967397, 2022).
acute kidney injury (7 papers, 2022 to 2025). Sudden and sustained deterioration of the kidney function characterized by decreased glomerular filtration rate, increased serum creatinine or oliguria. "Cold-inducible RNA-binding protein (CIRBP) expression has been linked to acute kidney injury, suggesting its potential as a new biomarker for transplanted kidney function." (PMID 39896811, 2024). "The mechanism by which extracellular cold-inducible RNA-binding protein (eCIRP) aggravates renal ischemia/reperfusion (RIR) injury leading to acute kidney injury (AKI) is poorly understood." (PMID 41583448, 2025). "The involvement of cold-inducible RNA-binding protein (CIRBP) in acute kidney injury has been suggested in another research, which proposed that ferritinophagy-mediated ferroptosis may be responsible for the enhanced ischemic kidney injury observed in the presence of CIRBP." (PMID 37840106, 2023).
bladder cancer (7 papers, 2018 to 2025). "The depletion of CIRBP using RNAi suppressed HIF1α levels to reduce the proliferation and migration of bladder cancer cell lines." (PMID 30717305, 2019). "A recent study has described a role for the cold-inducible RNA-binding protein (CIRBP) as a novel modulator of HIF1α translation in human bladder cancers." (PMID 30717305, 2019). "In this study, we investigated the role of CIRBP in human bladder cancer (BCa), indicating that CIRBP is overexpressed in BCa tissues and cell lines to promote proliferation and migration." (PMID 30315244, 2018). "CIRBP has been identified as an important oncogene that plays critical roles in proliferation, invasion, and metastasis in prostate cancer, liver cancer, breast cancer and bladder cancer." (PMID 34490236, 2021). "Taken together, our study indicated that CIRBP could be a novel oncogene in human bladder cancer inducing transcription of HIF-1α, which could inhibit expression of methylated PTGIS." (PMID 30315244, 2018). "However, recent studies found that CIRBP was overexpressed in prostate cancer, liver cancer, breast cancer, and bladder cancer and was involved in upregulating telomerase activity, promoting proliferation, inhibiting apoptosis, and promoting epithelial-mesenchymal transition (EMT)." (PMID 34490236, 2021).
Cerebral ischemia (7 papers, 2016 to 2025). Restriction of arterial blood supply to the brain associated with insufficient oxygenation to support the metabolic requirements of the tissue. "CIRBP is a neuroinflammatory mediator that is typically released by microglia cells in response to physiological stressors, including cerebral ischemia, alcohol exposure, and neuronal amyloid-β." (PMID 40779572, 2025).
breast carcinoma (6 papers, 2017 to 2025). "As a tumor promoter, CIRBP can promote proliferation and reduce apoptosis in breast cancer, prostate cancer, and lung carcinoma cells (A549) by target mRNA." (PMID 36013308, 2022). "To test the potential of CIRBP-mediated regulation of these targets in breast cancer development, we focused on Cystatin C (CST3), one of the most highly interconnected genes, encoding a protein that displays tumor suppressive capacities." (PMID 33172965, 2021). "Altogether, the results indicate that we have identified novel targets of CIRBP in human luminal breast cancer cells." (PMID 33172965, 2021). "To understand the role of CIRBP in luminal breast cancer, we perform the first genome-wide identification of CIRBP targets in cancer, and provide a repository of novel targets with potential relevance in breast oncogenesis." (PMID 33172965, 2021). "Our data provide a resource of CIRBP targets in breast cancer, and identify CST3 as a novel downstream mediator of CIRBP function." (PMID 33172965, 2021). "We find that CIRBP transcript levels correlate with breast cancer subtype and are an indicator of luminal A/B prognosis." (PMID 33172965, 2021). "Here we show that the RNA binding protein CIRBP displays pro-oncogenic properties in breast cancer, consistent with previous reports." (PMID 33172965, 2021). "Analysis of CIRBP expression along these subtypes revealed a higher transcript expression in less aggressive hormone-positive (ER+PR+) breast cancer samples present in TCGA and METABRIC databases." (PMID 33172965, 2021). "Among them, we identify CST3 as a functionally relevant target that is down-regulated by CIRBP to promote the tumorigenic properties of breast cancer cells." (PMID 33172965, 2021). "In order to select an appropriate cell system to study the function and targets of CIRBP in breast cancer, we next explored CIRBP protein levels in a set of breast cancer cell lines." (PMID 33172965, 2021). "We first validated breast cancer as a suitable model to study CIRBP-mediated regulation." (PMID 33172965, 2021). "Importantly, CIRBP transcript levels correlate with poor prognosis in the most frequent luminal A/B breast cancer subtype." (PMID 33172965, 2021). "Here, we use an ex vivo breast cancer model to identify CIRBP targets and mechanisms." (PMID 33172965, 2021). "We next focused on breast cancer, which had the highest absolute number of CIRBP alterations." (PMID 33172965, 2021). "In order to identify functionally relevant CIRBP targets in breast cancer, we evaluated changes in the transcriptomes of MCF-10A and MCF-7 cells after overexpression and depletion of CIRBP, respectively, by RNA-seq analysis." (PMID 33172965, 2021). "We provide proof-of-principle analysis showing that one of these novel targets, Cystatin C (CST3) is a functionally relevant CIRBP target in breast cancer, as depletion of CST3 abrogates the deleterious effects of CIRBP depletion." (PMID 33172965, 2021).
ischemia (6 papers, 2019 to 2023). A hypoperfusion of the BLOOD through an organ or tissue caused by a PATHOLOGIC CONSTRICTION or obstruction of its BLOOD VESSELS, or an absence of BLOOD CIRCULATION. "Expression of both CIRBP and HADHB was upregulated after hindlimb ischemia in mice." (PMID 30665182, 2019).
prostate carcinoma (6 papers, 2017 to 2022). A carcinoma that arises from epithelial cells of the prostate gland. "In addition, knockdown of CIRBP has been found to enhance the chemosensitivity of prostate cancer cells thus threatening cancer cell survival." (PMID 35541895, 2022).
cognitive deficits (5 papers, 2019 to 2024). "Genetic enrichment of CIRBP in hippocampal neurons CIRBPTg mice bred with Emx1-Cre mice attenuates hypoxia-induced cognitive deficits and neuronal degeneration." (PMID 38388728, 2024). "Recent findings suggest that induction of cold-inducible RNA-binding protein (Cirbp) overexpression in the hippocampal region attenuates HH exposure-induced hippocampal dendritic spine injury and cognitive impairment in mice." (PMID 37731540, 2023).
colon cancer (5 papers, 2013 to 2022). "Yang and coworkers identified CIRBP-bound transcripts by passing mRNA isolated from UVC-irradiated colon cancer cells over immobilized CIRBP in vitro." (PMID 23437386, 2013).
ovarian carcinoma (5 papers, 2006 to 2022). A malignant neoplasm originating from the surface ovarian epithelium. "Given the limited evidence it isdifficult to hypothesise a role for CIRBP in ovarian cancer.However, it is tempting to speculate that loss of CIRBP in ovariansurface epithelium may result in increased susceptibility to the DNA damagingeffects of hormones thereby increasing risk of tumor initiation." (PMID 21423607, 2011). "A large sample of ovarian cancer microarray study found that the expression of CIRBP was downregulated in ovarian cancer; further, in vitro cell experiments showed that the upregulation of CIRBP significantly inhibited the proliferation of ovarian cancer cells." (PMID 36061308, 2022). "In our analyses, CIRBP is downregulated in proestrusevening and restored in estrus morning, downregulated in expression array studiesand lost in array CNA studies of ovarian cancer." (PMID 21423607, 2011). "Among all these RBP genes, only four showed deletion in more than 5% of TCGA ovarian cancer samples, including transcription factor BTF3, sorbin and SH3 domain-containing protein 2 (SORBS2), cold-inducible RNA-binding protein (CIRBP), and RNA-binding protein MEX3D (MEX3D)." (PMID 29548303, 2018). "An effect of cold-inducible RNA binding protein on reducing cell doubling time was confirmed in our laboratory following transfection of the full-length cDNA into ovarian cancer cells (data not shown)." (PMID 16969345, 2006).
pancreatic cancer (5 papers, 2017 to 2024). "Associations of CIRBP expression with clinicopathological factors in pancreatic cancer patients." (PMID 34490236, 2021). "This indicates that cold induces CIRBP expression and then activates ferroptosis, thus inhibiting the growth of pancreatic cancer cells." (PMID 36061308, 2022). "The expression of CIRBP in pancreatic cancer tissues was slightly lower than that in normal tissues, and the high expression of CIRBP was beneficial to survival." (PMID 36061308, 2022). "CIRBP is a cold-induced RNA-binding protein, so pancreatic cancer cells were treated with cold, and it was found that cold induction did significantly promote the expression of CIRBP." (PMID 36061308, 2022). "CIRBP is a cold-induced protein that plays a key role in many physiological and pathological processes, but its role in pancreatic cancer is still unclear." (PMID 36061308, 2022). "Our in vitro studies show that increased CIRBP expression in pancreatic cancer cells facilitates their proliferation." (PMID 34490236, 2021). "Together, these data suggest that reduced CIRBP expression in pancreatic tumor cells improves their sensitivity to gemcitabine treatment." (PMID 34490236, 2021). "Therefore, the research further used immunohistochemistry to detect the expression location of CIRBP in pancreatic cancer tissues." (PMID 36061308, 2022). "This study found that the expression of CIRBP in pancreatic cancer tissues was lower than that in adjacent normal tissues and the high expression of CIRBP was beneficial to survival, indicating that CIRBP exerts a tumor suppressor function in pancreatic cancer." (PMID 36061308, 2022). "In pancreatic cancer cell lines, we demonstrated that CIRBP overexpression promoted PDAC cell proliferation and metastasis, and these effects could be reversed by CIRBP knockdown." (PMID 34490236, 2021). "To test whether CIRBP is involved in the resistance of PDAC to gemcitabine treatment, we used gemcitabine to treat pancreatic cancer cells with different levels of CIRBP expression." (PMID 34490236, 2021). "As CIRBP exhibits a strong association with tumorigenesis in several types of cancers, we evaluated the expression levels of CIRBP in pancreatic cancer tissue microarrays containing 90 specimens of primary pancreatic cancer and 60 specimens of normal adjacent pancreatic tissue." (PMID 34490236, 2021). "Together, these data show that CIRBP knockdown reduces the malignancy of pancreatic cancer cells." (PMID 34490236, 2021). "We then tested whether the levels of CIRBP in pancreatic cancer cells will influences in vivo tumor growth." (PMID 34490236, 2021). "Indeed, knockdown of CIRBP sensitized pancreatic tumors to gemcitabine treatment by diminishing DYRK1B expression and increasing the ratio of ERK/p38 activity." (PMID 34490236, 2021). "Therefore, CIRBP may play different roles in different tumor progression, and its role in pancreatic cancer is still poorly studied." (PMID 36061308, 2022).